STEAP3 (STEAP3 metalloreductase)
Diseases named in the same sentence as STEAP3 in open-access papers (continued):
Sharing a sentence is not in itself a finding about the gene and the disease.
cancer (32 papers, 2004 to 2025). A tumor composed of atypical neoplastic, often pleomorphic cells that invade other tissues. "cBioPortal database analysis showed that missense mutations were the main type of STEAP3 gene mutations in pan‐cancer." (PMID 37344930, 2023). "Considering the abnormal STEAP3 expression observed in different cancers, we analyzed mutations in the STEAP3 genes." (PMID 37344930, 2023). "We discovered a positive link between STEAP3 and immune‐associated pathways in diverse cancers, particularly in PRAD, ACC, LGG, KIRC, LIHC, LUSC, GBM, and THYM." (PMID 37344930, 2023). "Analyses of patients' survival status confirmed that STEAP3 was a risk factor in the onset and progression of many different types of cancer." (PMID 37344930, 2023). "Cancer cells require considerable amounts of iron due to rapid proliferation; STEAP3 encodes protein functions as an iron transporter, which may regulate intracellular iron storage and help tumors grow in iron-deficient environments." (PMID 34692847, 2021). "Importantly, Steap3 is known to be very critical to the metal homeostasis and linked to multiple diseases including cancer." (PMID 32055716, 2020). "The TIMER online analysis database was used to examine the expression of SERPING1 and STEAP3 in different types of cancer." (PMID 39853609, 2025). "STEAP3 is also a potential candidate biomarker for several cancers and a potential target for new immunotherapeutic strategies for disease attenuation or treatment." (PMID 40358178, 2025). "Recent studies have emphasised STEAP3's regulatory role in ferroptosis via iron metabolism, establishing it as a pivotal factor in cancer biology." (PMID 39853609, 2025). "Considering the close relationship between STEAP3 and cellular iron homeostasis, its role in a variety of cancers has been extensively studied." (PMID 38440354, 2024). "By analyzing RNA-seq data from TCGA and GTEx databases, we found that STEAP3 was generally highly expressed in pan-cancer tissues." (PMID 38440354, 2024). "In this study, we found that STEAP3 was abnormally expressed in various types of cancers by using information from several public databases." (PMID 38440354, 2024). "As part of our investigation into the possible functions of STEAP3 in malignancies, we conducted a comprehensive analysis to examine the prognostic value and immune features of STEAP3 in human pan‐cancer." (PMID 37344930, 2023). "Nonetheless, a complete pan‐cancer investigation of the prognostic significance and immune properties of STEAP3 is currently unavailable." (PMID 37344930, 2023). "Then, utilizing single‐cell sequencing data from the CancerSEA database, we investigated the correlation between STEAP3 expression and 14 cancer functional states, and 93 475 cancer single cells from 74 single‐cell data sets were included for further analysis." (PMID 37344930, 2023). "As per the findings, there was a strong correlation between STEAP3 expression and the degree of infiltration of most immune cells in pan‐cancer." (PMID 37344930, 2023). "Given STEAP3's specific functions in malignancies and its therapeutic potential, the prospects of its use as a pan‐cancer biomarker are particularly significant." (PMID 37344930, 2023). "STEAP3 expression has a positive correlation with the expression of ICGs in a majority of cancers, particularly in PRAD, GBM, LGG, KIRP, KIRC, and KICH." (PMID 37344930, 2023). "Considering the intra-tumoral heterogeneity, we continued to explore the relevance of STEAP3 expression across 14 functional states in cancers at single-cell resolution." (PMID 37009153, 2023). "By integrating the clinical information of ccRCC patients, we investigated the effect of STEAP3 expression on the prognosis of pan-cancer." (PMID 36424540, 2022).
cancer (continued). "In this study, by integrating information from multiple public databases, we found that STEAP3 is abnormally expressed in various types of cancer, and its abnormal expression is significantly related to the prognosis of cancer patients." (PMID 36424540, 2022). "Recently, given the close relationship between STEAP3 and cellular iron homeostasis, its important role in a variety of cancers has been extensively studied." (PMID 36424540, 2022). "Overexpression of STEAP3 has been proved to be involved in tumor progression and predicts poor prognoses in several human cancers." (PMID 34741044, 2021). "Then, analysis of STEAP3 expression with the TNMplot showed that STEAP3 mRNA expression was lower in cancer tissues from gene chip data (p = 1.77e-82) and RNA-seq data (p = 3.22e-57)." (PMID 34790664, 2021). "It has been reported that STEAP3 overexpression facilitates iron uptake, maintains iron storage in cancer cells and supports cancer cell proliferation under hypoferric conditions." (PMID 33092599, 2020). "STEAP3, also known as STAMP3 and TSAP6 is shown to be expressed at low levels in all tissues but generally decreased in cancer." (PMID 31393902, 2019). "Studies on STEAP3 have focused on its roles in cancer and cellular immunity." (PMID 40358178, 2025). "Then, we measured the protein expression of STEAP3 in various cancers in the HPA database." (PMID 37344930, 2023). "Compared with normal tissues, STEAP3 is significantly upregulated in 22 cancer types in TCGA database, suggesting that STEAP3 may function as a key regulator in cancers." (PMID 37344930, 2023). "However, the clinical significance and biological function of STEAP3 in human cancers remain poorly understood." (PMID 37009153, 2023). "STEAP3 may play a role in cancer development, progression, and immunotherapy; however, few studies have explored its significance in cancer research." (PMID 37344930, 2023). "In a diverse range of cancers, STEAP3 might serve as a biomarker for determining the prognosis as well as a predictor of immunotherapy responsiveness." (PMID 37344930, 2023). "We analyzed the expression profile of STEAP3 in pan-cancer through the GENT2 database." (PMID 36424540, 2022). "Furthermore, enhanced nuclear expression of STEAP3 promotes cancer cell proliferation by enhancing stemness phenotype and accelerating G1/S transition through regulating intracellular signaling and facilitating nuclear trafficking of EGFR." (PMID 34741044, 2021). "STEAP3 may function as pro- and anti-cancer gene, which depends on the tissue type as well as the context." (PMID 34790664, 2021). "Recently, the vital roles of STEAP3 in cancers have been extensively studied." (PMID 34790664, 2021). "The up-regulation of STEAP2 and STEAP3 expression in cancers may foster the transformed phenotype through their ability to promote iron assimilation." (PMID 34988012, 2021). "Interestingly, the expression of STEAP2 and STEAP3 is similar in different types of malignant tumors, with high or medium levels." (PMID 32802887, 2020). "Recently, studies on STEAP3 have emerged, predicting the important role of STEAP3 in cancers." (PMID 32802887, 2020). "The expression of STEAP1 and STEAP2 is up-regulated in some cancer types, such as prostate, bladder, colon, pancreas, ovary, testis, breast, etc., but their clinical effects for cancer therapy are unclear.Under hypoferric condition, STEAP3 expression was up-regulated to maintain tumor growth." (PMID 29789480, 2018). "STEAP3-induced TCTP secretion may also sensitize cancer cells to apoptosis." (PMID 39668818, 2024). "Furthermore, it was discovered that STEAP3 was highly overexpressed in people with TNBC and associated with overall survival rates, laying the groundwork for the eventually targeted therapy of individuals with this form of cancer." (PMID 37064114, 2023).
cancer (continued). "Herein, we conducted an in‐depth pan‐cancer investigation of STEAP3's role in cancer prognosis and immunology, demonstrating that STEAP3 could potentially serve as a predictive biological marker as well as a predictor of the responsiveness to immunotherapy in a variety of malignancies." (PMID 37344930, 2023). "We conducted single‐cell analysis using cancer sample files from the TISCH database to identify the principal cell types that express SERPING1 and STEAP3 inside the TME." (PMID 39853609, 2025). "The result indicate a concentration-dependent inhibition in STEAP3, DMT1, FPN1, and TFR1 expression upon 6-gingerol treatment, suggesting the capacity of 6-gingerol to suppress iron transport in cancer cells." (PMID 37998363, 2023). "What’s more, the differential expression of STEAP3 between LIHC and its corresponding non-cancer tissues can be confirmed by the data from TCGA (p < 0.001)." (PMID 34790664, 2021). "Nevertheless, a systematic review of STEAP3's predictive significance and immune features across all cancer types has not been documented." (PMID 37344930, 2023). "In addition to HCC cells, similar interaction between STEAP3 and EGFR was observed in HEK293, suggesting it might be a common functional role of STEAP3 in human cancers." (PMID 34741044, 2021). "For certain cancer types without matched normal tissues in the TMIER2.0 database, we further explored the expression profile of STEAP3 using the Xiantao tool." (PMID 37009153, 2023).
infection (4 papers, 2010 to 2025). The state of being infected such as from the introduction of a foreign agent such as serum, vaccine, antigenic substance or organism. "In the 2D cell culture system, we identified the underlying molecular mechanisms, demonstrating that STEAP3 primarily interacts with viral receptors during the early stage of infection, suggesting its antiviral function is mediated through modulation of receptor interactions." (PMID 40836050, 2025). "Using this integrated approach, we found that STEAP3 knockdown significantly increased viral entry and infection, particularly in enterocytes and enteroendocrine cells." (PMID 40836050, 2025). "Knockdown of STEAP3 obviously increased the infection of wild-type (WT) SARS-CoV-2 S entry viruses in colon organoids." (PMID 40836050, 2025). "There is a fivefold higher induction of Steap3 and Dmt1 during infection with Francisella (p = 0.0001) when compared to infection with wild-type Salmonella (p = 0.67)." (PMID 20184753, 2010). "Consequently, decreased STEAP3 expression significantly increased the viral titer in RD cells after EV-A71 infection." (PMID 40836050, 2025). "The 2D system enabled high-resolution mechanistic interrogation of STEAP3-dependent viral entry processes, while the patient-derived 3D colon organoid model recapitulated the architectural and cellular complexity of intestinal tissue, allowing spatially resolved assessment of infection patterns." (PMID 40836050, 2025). "The interaction between STEAP3 and SCARB2 increased at 0 and 1 h post-EV-A71 infection." (PMID 40836050, 2025). "Similarly, STEAP3 knockdown attenuated the inhibitory effect of FAC on viral titers in RD cells at both 12 and 24 h post-infection." (PMID 40836050, 2025). "STEAP3, the only STEAP family member to be highly expressed in macrophages, has been shown to be down-regulated by lipopolysaccharide administered as a surrogate for infection in rats." (PMID 35083470, 2021).
STEAP3 also shares sentences with these, for which no sentence is quoted: pancreatic cancer (6 papers); malignant glioma (4); iron overload (2); triple-negative breast carcinoma (2); alcohol dependence (1); anaplastic large cell lymphoma (1); asthma (1); astrocytoma (1); benign prostatic hyperplasia (1); beta thalassemia (1); blood cancer (1); brain cancer (1); cervix cancer (1); coronary artery disease (1); Crohn disease (1); Erdheim-Chester disease (1); head and neck squamous cell carcinoma (1); heart failure (1); Hepatic Injury (1); kidney cancer (1); Langerhans cell histiocytosis (1); lung squamous cell carcinoma (1); osteoarthritis (1); pancreatic adenocarcinoma (1); pheochromocytoma (1); prostate tumors (1); renal diseases (1); schizophrenia (1); skin cutaneous melanoma (1); thymoma (1).
A further 2 diseases each share a sentence with STEAP3 in 1 paper.